CCR8 (C-C motif chemokine receptor 8)
Diseases named in the same sentence as CCR8 in open-access papers (continued):
Sharing a sentence is not in itself a finding about the gene and the disease.
colitis (9 papers, 2014 to 2025). Inflammation of the colon. "Different from the closely related molecule CCR4, which has been previously shown to drive pathogenic inflammatory reactions in mouse colitis models, Ccr8−/− mice developed highly increased mucosal damage compared to control mice." (PMID 33613532, 2020). "Given that rather NKp46+ ILC1s than ILC3s have been shown to be necessary for the control of DSS colitis, this indicates that reduced frequencies of ILC1s are causatively involved in the exacerbated disease phenotype in Ccr8−/− mice." (PMID 33613532, 2020). "Conversely, CCL1 treated mice displayed similar susceptibility to mucosal damage as control-treated Ccr8−/− mice consistent with a gut protective functional role of CCL1/CCR8 signaling during experimental colitis." (PMID 33613532, 2020). "Colitis-associated inflammation in CCR8-/- mice was less severe than that in WT mice, as evidenced by less peritoneal adhesion to the colon and lower histological scores indicating fewer transmural ulcers, but there were no significant decreases in ulcer area." (PMID 24714157, 2014). "Further investigation demonstrated that MLB cells from colitis rats were recruited to the colon by intra-intestinal T cells through the Ccr8-Ccl1 axis, where they subsequently exacerbated inflammatory responses via enhanced differentiation." (PMID 40331987, 2025). "MLB cells exhibited a tendency to migrate to the intestine and exacerbate colitis through the Ccr8-Ccl1 axis, potentially by contributing to intestinal T cell-mediated inflammation." (PMID 40331987, 2025). "Although the present study did not detect alterations in CXCL13 and CXCR5 expression in MLB cells from TNBS-induced colitis rats, we observed upregulated mRNA expression of Ccr8, a receptor for the T cell-derived chemokine Ccl1, in these rats." (PMID 40331987, 2025). "On the other hand, colitis rats receiving feed with high-molar-mass oat beta-glucan (CβGh+) resulted in higher expression of only four genes (Ccl19, Ccr4, Ccr8, Cxcl9)." (PMID 35163326, 2022). "Consistently, a prior study has reported that M2-EVs can alleviate intestinal inflammation in DSS-induced colitis by mediating the CCL1/CCR8 axis." (PMID 34895044, 2021). "Possibly, CCR8 expressing Treg are more prominent immunoregulatory factors in T cell dependent models of colitis such as chronic DSS colitis or T cell transfer colitis." (PMID 33613532, 2020). "In order to further characterize this complex immune cell network in intestinal inflammation, we investigated the contribution of the chemokine receptor CCR8 to development of colitis using a mouse model of experimental inflammation." (PMID 33613532, 2020). "Noteworthy, transcripts of IL-18 binding protein and IDO1 were highly downregulated in Ccr8−/− mice with colitis." (PMID 33613532, 2020). "In the innate immune cell compartment, the numbers of innate lymphocytes were reduced in the lamina propria of Ccr8−/− mice with DSS colitis compared to controls." (PMID 33613532, 2020). "We next used RNAseq-based gene expression profiling to investigate the impact of Ccr8 inactivation on the global colonic transcriptome in mice with DSS colitis." (PMID 33613532, 2020). "To establish further evidence that the protective role of CCL1/CCR8 signaling during acute colitis is primarily driven by innate immune system mediated mechanisms, we overexpressed CCL1 in lymphopenic Rag1−/− mice, which lack T and B cells, but harbor a functional ILC compartment." (PMID 33613532, 2020). "Additionally, we found that M2b macrophage exosomes, carrying the CCL1 protein to the colon, interact with CCR8 to promote Th2 polarization and increase Treg percentages, thereby relieving colitis." (PMID 31749791, 2019).
colitis (continued). "After 7 days of induced colitis, upregulation of the expression of 22 genes (Ccl2, Ccl3, Ccl4, Ccl5, Ccl6, Ccl7, Ccl12, Ccl17, Cxcl1, Cxcl2, Cxcl6, Cxcl9, Cxcl11, Ccr1, Ccr2, Ccr3, Ccr5, Ccr8, Cxcr2, Csf3, Osm, and Spp1) was observed in the CβG− group compared to the HβG- control group." (PMID 35163326, 2022). "Because CCR8 is expressed on Foxp3+ Treg and has been implicated in their suppressive capacity in autoimmunity and cancer, it was tempting to speculate that dysregulated Treg functions contributed to exacerbated DSS colitis in Ccr8−/− mice." (PMID 33613532, 2020). "Similarly, mucosal CCR8 transcripts were increased in the context of dextrane sodium sulphate (DSS) induced colitis in mice indicating that this chemokine receptor might be somehow involved in the development of inflammatory bowel disease." (PMID 33613532, 2020). "In the present study, we found increased mRNA expression of genes related to inflammatory and immune responses, including Cd27 and Cd40, as well as the chemotactic receptor Ccr8, in MLB cells from colitis rats." (PMID 40331987, 2025). "We therefore next compared the frequencies of IFN-γ-producing lymphocytes in LPMC of Ccr8+/+ and Ccr8−/− mice with DSS colitis using flow cytometry." (PMID 33613532, 2020). "Further experiments revealed that this gut protective function of CCR8 seems to be selectively mediated by the chemotactic ligand CCL1, which was particularly produced by intestinal macrophages during colitis." (PMID 33613532, 2020). "In this study here, we explored the functional role of the CC chemokine receptor CCR8 and its activation by the two known ligands CCL1 and CCL8 in DSS colitis, a widely used mouse model of IBD resembling important features of UC." (PMID 33613532, 2020). "The M2b macrophage exosomes exerted protective effects on DSS-induced colitis, mainly mediated by the CC chemokine 1 (CCL1)/CCR8 axis." (PMID 31749791, 2019). "The results also suggest that M2b macrophage exosomes exert protective effects in DSS-induced colitis, which are mainly mediated by the CCL1/CCR8 axis." (PMID 31749791, 2019). "In addition, the expression of CCR8 and its ligand CCL1 is upregulated in patients with UC and in the DSS-induced colitis model." (PMID 35707544, 2022). "Interestingly, further experiments clearly suggested that these CCR8-mediated tissue protective effects are exclusively mediated by the ligand CCL1, while CCL8-treatment of wildtype mice rather exacerbated colitis." (PMID 33613532, 2020). "Indeed, in the colitis model, activation of the CCL1/CCR8 system is limited to the serosal side of the colon or the peritoneal cavity." (PMID 24714157, 2014). "In this setting, CCL8 treatment resulted in increased colitis even in the absence of CCR8 supporting the concept that this chemokine seemingly at least under these particular experimental settings employs other CCR8 independent signal transduction pathways to amplify intestinal inflammation in vivo." (PMID 33613532, 2020). "However, antibody-mediated IL-18 neutralization did not rescue Ccr8−/− from severe intestinal pathology indicating that excessive IL-18 signaling is not a main driver of colitis in this strain." (PMID 33613532, 2020). "In the case of colitis, the potential for R243 to block both CCL2 (MCP-1)/CCR2-driven chemotaxis and CCL1 might enhance the anti-inflammatory effect in comparison with that of CCR8-/- mice." (PMID 24714157, 2014). "Unlike parasite infection, the major source of CCL1 during DSS-induced colitis is macrophages rather than ILC2s, but CCL1/CCR8 signaling similarly protects hosts from both parasite infection and acute intestinal damage in a DSS colitis model." (PMID 35707544, 2022). "However, our results indicate there are two differences: 1) Pam3CSK4-induced IL-10 production is abrogated in CCR8-/- PMφ but not with R243 treatment, and 2) suppression of TNBS colitis in CCR8-/- mice is not as evident as that in R243-treated mice." (PMID 24714157, 2014).
lung carcinoma (9 papers, 2017 to 2025). "Our recent analyses of lung cancer patients suggested that the accumulation of CCR8+ Tregs was associated with the impaired cytotoxic function of neighboring CD8+ T cells and a poor prognosis 16,22." (PMID 41323783, 2025). "Using flow cytometry and public mRNA database analysis, our previous study showed high CCR8+ Treg infiltration within tumors that was associated with poor prognosis in lung cancer patients." (PMID 38783281, 2024). "CCR8+ Tregs were highly activated and infiltration of CCR8+ Tregs in tumors was associated with poor prognosis in lung cancer patients." (PMID 35354899, 2022). "CCL18 is a cytokine released from tumor-associated macrophages that binds to CCR8 and has been implicated in the epithelial-mesenchymal transition of breast, pancreatic and lung cancers." (PMID 29100308, 2017). "Furthermore, a high level of CCR8+ Tregs was associated with poor prognosis in patients with breast, bladder, or lung cancer 13,16,22,28." (PMID 41323783, 2025). "Our previous study also reported that CCR8+ Tregs are involved in the tumor immunosuppressive microenvironment in lung cancer, including LSCC." (PMID 38783281, 2024). "We have previously demonstrated that human CCR8+ Tregs from lung cancer TILs or expanded from peripheral blood mononuclear cells have potent inhibitory activity against CTL function in vitro." (PMID 38783281, 2024). "In conclusion, we revealed the pathophysiological characteristics of CCR8+ Tregs in human lung cancers and their inhibitory effect on CD8 T cells." (PMID 35354899, 2022). "We also revealed the anti-cancer efficacy of CCR8-targeted therapy using a murine lung cancer model." (PMID 35354899, 2022). "In this study, we performed a detailed investigation of CCR8+ Tregs in human lung cancer and demonstrated that they have highly suppressive functions against CD8 T cells." (PMID 35354899, 2022). "This is first report to reveal the direct suppressive functions of CCR8+ Tregs against CD8 T cells using human lung cancers and induced human Tregs." (PMID 35354899, 2022). "To determine the clinical significance of CCR8+ Tregs in lung cancer, we evaluated the frequency of CCR8+ Tregs in tumor-infiltrating CD45+ cells in 50 lung cancer patients by flow cytometry and analyzed the correlation with clinical stage and outcome." (PMID 35354899, 2022). "In this study, we examined the involvement of CCR8+ Tregs in human lung cancer and their functional profiles." (PMID 35354899, 2022). "The data suggest the potential impact of CCR8+ Tregs on cancer immunity and the potential of CCR8-targeted therapy for lung cancer immunotherapy." (PMID 35354899, 2022). "We found that CCR8+ Tregs in human lung cancer exhibited a similar suppressive expression profile to previous studies, and further revealed that they are in a strongly activated state and enhance chemokine signaling." (PMID 35354899, 2022). "We finally evaluated the potential anti-tumor activity of CCR8-targeted therapy in a murine model of lung cancer." (PMID 35354899, 2022). "We first analyzed CCR8 expression on immune cells obtained from 11 lung cancer patients by flow cytometry." (PMID 35354899, 2022). "In this study, we used a subcutaneous transplantation model because of the difficulty in conducting stable orthotopic tumor transplantation, but the evaluation of CCR8-targeted therapy in an orthotopic lung cancer model is another issue for future study." (PMID 35354899, 2022). "Furthermore, preclinical studies in several murine tumor models, including lung carcinoma, have demonstrated that depletion of CCR8+ Tregs by anti-CCR8 antibody administration resulted in a marked anti-tumor effect." (PMID 38783281, 2024). "Here, we investigated the features of CCR8+ Tregs in lung cancer patients." (PMID 35354899, 2022). "Together, these findings may help to provide evidence and a foundation for the development of CCR8-targeted immunotherapy for cancers including lung carcinoma." (PMID 35354899, 2022).
lung carcinoma (continued). "Finally, we revealed the therapeutic potential of targeting CCR8 for cancer treatment using a murine model of lung cancer." (PMID 35354899, 2022). "Another common theme not only observed in gastric cancer but in the TME from various indications including breast, liver, colorectal, and lung cancer is the appearance of a cluster of activated and immune suppressive regulatory T cells expressing activation markers such as 4-1BB and CCR8." (PMID 36550535, 2022). "Finally, we demonstrated the therapeutic effect of targeting CCR8 in a murine model of lung cancer." (PMID 35354899, 2022). "We provide evidence that CCR8-targeted therapy may be effective for the treatment of lung cancer." (PMID 35354899, 2022). "This study focused on CCR8+ Tregs and their interaction with CD8+ T cells in the tumor microenvironment of human lung cancer." (PMID 38783281, 2024). "Recent studies have shown that the chemokine receptor CCR8 is overexpressed in tumor-infiltrating Tregs of patients with different cancers, including breast, colon, and lung cancers, with no major CCR8-positivity found on peripheral Tregs." (PMID 40186298, 2025). "First, using public lung cancer mRNA expression databases, we revealed that CCR8-high tumors showed reduced T cell- and APC-related genes and significantly lower naïve and effector CD8 T cell scores compared with CCR8-low tumors." (PMID 35354899, 2022). "We next divided 50 lung cancer patients into the CCR8-high and low groups based on the median value of the percentage of CCR8+ Tregs in CD45+ cells and found that the disease-free survival (DFS) of the CCR8-high group was significantly shorter than that of the CCR8-low group (p = 0.011)." (PMID 35354899, 2022).
Autoimmunity (8 papers, 2017 to 2024). The occurrence of an immune reaction against the organism's own cells or tissues. "While near complete loss of the Treg cell pool in KP-DTR mice led to systemic autoimmunity and inflammation, VEGF blockade coupled with CCR8 antibody-mediated depletion of intratumoral Treg cells showed impressive therapeutic efficacy with no adverse effects." (PMID 37127830, 2023). "Results also indicated that anti-CCR8 mAbs promote minimal autoimmunity compared to systemic Treg depletion." (PMID 35565306, 2022). "We conclude that CCR8 does not distinguish between dermal and epidermal memory T cells, whereas uniform expression on Treg cells suggests a role for CCR8 in the cellular control of skin-specific autoimmunity." (PMID 29427415, 2018). "This study also showed that CCL1 was upregulated by FOXP3+ Treg in the CNS in an EAE mouse model of multiple sclerosis, driving a feed-forward loop in which CCR8 expression was upregulated, in turn promoting Treg-mediated suppression of autoimmunity." (PMID 30024927, 2018). "Targeting CCR8 with anti-CCR8 mAb not only reduced multiclonal Tregs specifically in tumor tissues but also evoked strong anti-tumor immune responses without causing harmful autoimmunity." (PMID 39227959, 2024). "However, CCR8 is also expressed by peripheral Tregs and clearly plays a role in promoting their immunosuppressive activity, thus inhibiting autoimmunity." (PMID 30024927, 2018). "Moreover, targets such as CD37, CD47, B7-H6, CDC27, TCRVβ, and CCR8, when employed in CAR-T cells, present minimal risks of fratricide and autoimmunity." (PMID 38915099, 2024). "The safety and lack of autoimmunity secondary to CD4-AsiC knockdown of PITPNM3 or antibody inhibition of CCL18, PITPNM3 or CCR8 will need to be examined carefully to evaluate potential therapeutic applications." (PMID 28290464, 2017).
breast tumor (7 papers, 2017 to 2025). "In humans, immunosuppressive CCR8+ Tregs infiltrate breast tumors and CCR8 high expression is correlated with poor prognosis." (PMID 30930117, 2019). "In vivo efficacy studies were conducted using the EMT6 syngeneic breast tumor model, characterized by an immunosuppressive tumor microenvironment, assessing the antitumor effects of a CCR8-targeted small molecule (IPG7236) as monotherapy or in combination with anti–PD-L1 treatment." (PMID 41568381, 2025). "Finally, co-culture with breast tumor slides was found to substantially upregulate CCR8 mRNA in CD3/CD28-activated Tregs." (PMID 38231448, 2024). "However, a large fraction of Tregs and memory T cells express CCR8, which might recruit them to breast tumors." (PMID 28290464, 2017). "The tremendous impact of CCL1 on the accumulation of Tregs in the breast tumor environment is evident, as CCL1 serves as the functional ligand for CCR8." (PMID 38730579, 2024). "PITPNM3 has been proven to be a functional CCL18 receptor in breast tumor cells and T lymphocytes, while CCR6 and CCR8 have been proven to be expressed in T lymphocytes." (PMID 36418470, 2023).
colon carcinoma (7 papers, 2021 to 2025). "In the present study, CCR8 expression levels were through RT‐qPCR screened also in several human colon carcinoma cell lines." (PMID 38506205, 2024). "Anti-CCR8 monoclonal antibody (mAb) treatment of mice inoculated with CT26 colon carcinoma cells significantly reduced Tregs in tumors and enhanced intratumoral IFNγ expression." (PMID 34632244, 2021). "Notably, CCR8 blockade alone also did not affect the subcutaneous growth of MC38 colon carcinoma, a hot tumor that is known to be responsive to immunotherapy." (PMID 33589525, 2021). "In contrast, others have shown that CCR8 may be redundant for intratumoral Treg homing, as adoptively transferred Ccr8-knockout Tregs in mice inoculated with MC38 colon carcinoma cells did not display reduced potential of migrating into tumors." (PMID 34632244, 2021).
atherosclerosis (6 papers, 2019 to 2023). A disease characterized by the build-up of fatty material and calcium deposition in the arterial wall resulting in partial or complete occlusion of the arterial lumen. "In addition, a decrease in regulatory T cells was observed in the aorta of mice treated with CCR8-blocking antibodies and was associated with exacerbation of atherosclerosis." (PMID 37047399, 2023). "In the current study, both CCR4 and CCR8 are upregulated in IS current smoker patients, which may suggest a role of current smoking in increasing stroke injury by promoting atherosclerosis and platelet aggregation." (PMID 31436916, 2019). "After one week, the expression in the chemokine receptors CXCR4, CCR8, CCR5, and CCR2, which are all known to play an important role in inflammation and atherosclerosis development, was analyzed on the surface of various leukocyte subsets in the blood and spleen using flow cytometry." (PMID 34884827, 2021). "However, studies investigating the role of CCR8 on ILC2s in atherosclerosis are still lacking." (PMID 38179045, 2023).